INS (insulin)
Diseases named in the same sentence as INS in open-access papers (continued):
Sharing a sentence is not in itself a finding about the gene and the disease.
Insulin resistance (continued). "In general, BPA has been associated with increased glycated hemoglobin (HbA1c) levels in adults, greater serum insulin levels and insulin resistance, and higher risk of prediabetes and type 2 diabetes." (PMID 34948652, 2021). "This Type results from insulin resistance or insufficient insulin production, essentially associated with multihormonal disorders." (PMID 34361044, 2021). "Type 2 diabetes is associated with insulin resistance, which causes the compensatory expansion of pancreatic β-cells and increases plasma insulin levels." (PMID 34445786, 2021). "Non-insulin-dependent/type 2 diabetes mellitus is characterized by insulin resistance and/or abnormal insulin secretion (hyperinsulinemia), which subsequently cause abnormally high blood glucose levels (hyperglycemia)." (PMID 33652692, 2021). "Fetuin-A (Fet-A), classically considered a hepatokine, is a natural insulin inhibitor tyrosine kinase and is associated with insulin resistance and inflammation in rodents and humans." (PMID 33807959, 2021). "The authors gave evidence of an improved β-cell function and insulin secretion in these mice, thereby increasing plasma insulin, a hallmark of insulin resistance." (PMID 34638803, 2021). "Human APPswe/ind-transfected neuronal SH-SY5Y cells with insulin resistance were exposed to a high insulin concentration (1 μM) (SH-SY5YIR) to determine the mechanism underlying the insulin-sensitizing activity of Os-pep." (PMID 33849621, 2021). "Increased expression and activity of PKC isoforms are associated with impaired insulin signalling in subjects with insulin resistance." (PMID 34208786, 2021). "This association with T2DM independently of BMI, insulin resistance and other metabolic indices confirms that impaired insulin secretion is a result of genetic defect of TCF7L2." (PMID 34073870, 2021). "Gestational DM (GDM) is mainly caused by a blockage of insulin action by the pregnancy hormones, causing insulin resistance and hyperglycaemia." (PMID 34361044, 2021). "Hyperglycemia causes insulin resistance, which then triggers a compensatory mechanism that increases insulin levels, thus leading to hyperinsulinemia." (PMID 34202399, 2021). "Diabetes, caused by the deficiency of insulin secretion and/or insulin resistance and characterized by chronic hyperglycaemia, is currently one of the most important metabolic diseases worldwide." (PMID 34042263, 2021). "In the process of T2DM, the long-term high level of free fatty acids (FFAs) in the body causes excessive insulin secretion and then leads to insulin resistance in peripheral tissues." (PMID 34630099, 2021). "Briefly, prolactinoma, a pituitary cell cancer connected with insulin resistance caused by downregulating insulin receptors, is linked with decreased vaspin levels, which clearly links vaspin with insulin-level regulation in the body." (PMID 34359881, 2021). "Previous research has found that biomarkers related to obesity (eg, insulin and Homeostatic Model Assessment for Insulin Resistance) are more strongly associated with weekday digital technology use than weekend use in adolescents." (PMID 35143408, 2021). "Compared to BMI and insulin requirements, classical surrogates of insulin resistance, eGDR is a suitable and superior thrombotic risk indicator in T1D." (PMID 33730349, 2021). "Whereas elevated NEFA is often associated with insulin resistance, mirabegron treatment increased muscle type I fibers and capillary density, resulting in improved insulin sensitivity." (PMID 33571166, 2021). "An elevated LCAC content is associated with impaired insulin sensitivity in patients, and this association has been further characterized in animal models of insulin resistance." (PMID 34208786, 2021). "By contrast, elevated plasma concentrations of triacylglycerol-rich lipoproteins reflect increased fatty acid flux from adipose tissue, and are linked with diminution of insulin secretion and induction of insulin resistance in patient cohorts." (PMID 34203703, 2021).
Insulin resistance (continued). "Insulin resistance usually causes abnormal lipid metabolism in body, since insulin can promote lipoprotein decomposition." (PMID 34712684, 2021). "Another study reported that the effect of IRS1 polymorphism on hepatic insulin resistance and he showed decreased hepatic levels, reflecting reduced insulin signaling activity." (PMID 34449768, 2021). "Oxidative stress is associated with adiposity, impaired insulin signaling pathways, insulin resistance, and increased risk of cardiometabolic diseases." (PMID 33466692, 2021). "The present study also found that fasting PG levels in the 75-g OGTT were a risk factor for insulin therapy and fasting PG were correlated with insulin resistance." (PMID 33776619, 2021). "As strong associations have been established between NAFLD, T2DM and insulin resistance, the increase in insulin sensitivity with the use of GLP-1RA can have a valuable synergistic effect on improvement of both NAFLD and T2DM." (PMID 33897616, 2021). "A hallmark risk factor of MetS is insulin resistance (IR), which is an impairment of insulin function to promote glucose uptake in insulin-sensitive target tissues, such as skeletal muscle and adipose tissue, resulting in abnormal glucose homeostasis." (PMID 34578869, 2021). "The common thread between these risk factors is insulin resistance in the CNS, defined broadly in this context as impaired insulin activity in the CNS." (PMID 34545146, 2021). "AHI was positively associated with fasting plasma insulin (p = 0.033), an Insulin resistance parameter derived from IVGTT (p = 0.017) as well as measured by HOMA-IR (p = 0.018)." (PMID 33574418, 2021). "Obesity, metabolic stress, and inflammation in the adipose tissue environment are also associated with adipocyte insulin resistance, including reduced ability of insulin to inhibit lipolysis." (PMID 33610548, 2021). "Obesity induces insulin resistance, and consequently, type 2 diabetes, which is associated with fat accumulation and malfunction of insulin." (PMID 33918360, 2021). "The improvements in glycemia induced by weight loss are most likely to be seen early in the natural progression of T2DM when insulin resistance due to obesity has caused reversible β‐cell dysfunction but insulin secretory capacity remains relatively preserved." (PMID 34401196, 2021). "Empirical lifestyle index for hyperinsulinemia was directly associated with insulin resistance, insulin insensitivity, and hyperinsulinemia and was inversely associated with β-cells dysfunction." (PMID 33985566, 2021). "It acts on insulin sensitivity, and its plasma reduction is related to insulin resistance and glucose intolerance, predisposing to advanced liver injury." (PMID 33807959, 2021). "Using lifestyle modification in the form of exercise and weight loss, survivors can reduce insulin and insulin resistance through altered body composition." (PMID 34578984, 2021). "Glutamine:fructose-6-phosphate aminotransferase 1 (GFPT1) is the rate limiting enzyme in glucose metabolism by the hexosamine pathway (associated with impaired insulin secretion and insulin resistance)." (PMID 34827690, 2021). "Increased production of oxidants in the mitochondria causes insulin resistance and is associated with low levels of the antioxidant coenzyme Q in the insulin-resistant fat and muscle tissue mitochondria of mice." (PMID 34356303, 2021). "It is assumed that insulin resistance in metabolic syndrome is the vital cause of this linkage, as impaired insulin signaling contributes to the pathogenesis of AD." (PMID 34366841, 2021). "Insulin resistance promotes increased levels of circulating endogenous insulin and insulin-like growth factor levels associated with increased risks of high-grade prostate cancer and PCSM." (PMID 34169227, 2021). "The first two clusters were associated with reduced insulin secretion, and three clusters were associated with insulin resistance." (PMID 34677406, 2021).
Insulin resistance (continued). "The lower levels of insulin and insulin resistance in these patients indicated and strengthen the causative relationship." (PMID 33776997, 2021). "The obesity-enhanced immune cell infiltration is intimately linked to insulin resistance (IR) via interference with the insulin signaling pathway in adipose tissue and skeletal muscle." (PMID 34211580, 2021). "Intra-abdominal fat is strongly and independently associated with both insulin resistance and poor glycemic control, while the subcutaneous adipose tissue is thought to maintain insulin sensitivity." (PMID 34917687, 2021). "Plasma FABP4 levels in the first and second trimesters were positively associated with fasting insulin and homeostasis model assessment for insulin resistance (HOMA-IR) in the second trimester (both P < 0.001)." (PMID 34368366, 2021). "The sixth and ninth publications show the effects and underlying mechanisms of insulin and insulin resistance on polycystic ovary syndrome (PCOS) and PCOS complication depression." (PMID 34366917, 2021). "A number of studies have been performed to understand the molecular basis of insulin resistance (IR), a pathological alteration in insulin sensitivity linked to many metabolic disorders, such as type 2 diabetes." (PMID 34857871, 2021). "Multivariable analysis identified that TYK2PV was associated with fasting insulin ≤ 5 μIU/mL (odds ratio (OR) 3.63, p = 0.025) and C-peptide ≤ 1.0 ng/mL (OR 3.61, p = 0.028), and also lower insulin resistance (HOMA-IR ≤ 2.5; OR 8.60, p = 0.042)." (PMID 33799705, 2021). "Adult female offspring under normal diet display insulin resistance associated with increased insulin secretion." (PMID 35111136, 2021). "There is a growing body of evidence pointing to the benefits of intermittent fasting for glucose and insulin homeostasis, but this should be confirmed by further studies in population groups with (or at high risk) type II diabetes and insulin resistance." (PMID 33826120, 2021). "ANGPTL3 is expressed and release by the liver and works as a regulator of plasma triglyceride levels, positively associated with glycemia, and insulin levels in patients with insulin resistance." (PMID 33807959, 2021). "Type 1 and type 2 diabetes occur when β-cells are unable to meet the increased demand for insulin due to insulin deficiency and insulin resistance, respectively." (PMID 33746901, 2021). "High levels of insulin are a sign of insulin resistance caused by obesity; an abundance of adipose tissue reduces the sensitivity of cells to insulin, and islet cells are then stimulated to produce more insulin, resulting in hyperinsulinaemia." (PMID 33585429, 2021). "Less is known about insulin in the brain, or how insulin resistance relates to neuropathology, the underlying substrate of brain dysfunction." (PMID 33858515, 2021). "Collectively, we found that the genes SRR, PDE4B, and NFKB1A were directly and indirectly associated with insulin secretion, insulin resistance, and T2DM." (PMID 35046895, 2021). "Insulin resistance, defined as an impaired stimulation of insulin to targeted tissues, is a risk factor for a wide range of disorders and clinical concerns, including hypertension, type 2 diabetes, and cardiovascular disease." (PMID 34578862, 2021). "Insulin resistance is a hallmark of obesity-related pathologies that is driven by insulin signaling inactivation." (PMID 34956089, 2021). "High expression of phosphorylated mTORSer2448, phosphorylated S6K1Thr389, and phosphorylated IRS1Ser302 has been found in mice fed with BCAAs, which can block the normal conduction of insulin signaling and cause insulin resistance." (PMID 34447287, 2021). "Although the underlying mechanism responsible for insulin resistance is still uncertain, deficiencies in insulin signalling are considered either driving factors or primary signs predisposing to the development of T2D." (PMID 34243726, 2021).
Insulin resistance (continued). "20-HETE significantly impacts obesity associated with a high-fat diet, impaired insulin signaling, and insulin resistance (IR)." (PMID 34521427, 2021). "Obesity and insulin resistance are associated with alterations in nitric oxide level and insulin secretion." (PMID 34335851, 2021). "Insulin resistance also causes a decrease in the concentration of an insulin-sensitizing adipokine called adiponectin." (PMID 35010976, 2021). "Insulin resistance is a metabolic aberration causing an impairment of insulin to achieve its physiological effects, including the stimulation of glucose uptake and inhibition of hepatic glucose output." (PMID 35008779, 2021). "Type 2 DM is associated with lifestyle and genetic factors that cause insulin resistance, impaired biosynthesis and secretion of insulin, and reduced β-cell mass, resulting in a relative insufficiency of insulin activity." (PMID 34571886, 2021). "The close association between insulin secretion and insulin resistance leaves open the question which comes first." (PMID 34659123, 2021). "On the other hand, an excess of vWAT is associated with insulin resistance, and removal of vWAT during bariatric surgery improves insulin sensitivity." (PMID 34310946, 2021). "That was because being overweight and obese increased the risk of insulin resistance and further reduced insulin secretion as a function of the pancreas." (PMID 33708998, 2021). "T2D is thought to be a complication of metabolic syndrome caused by disorders of energy utilization and storage and characterized by insulin resistance and deficiency of insulin secretion." (PMID 34368359, 2021). "Insulin secretion disorders caused by pancreatic β-cell dysfunction and impaired insulin action caused by enhanced insulin resistance lead to hyperglycemia in T2DM." (PMID 33692782, 2021). "Insulin resistance (IR) is a condition in which normal concentrations of insulin cause a smaller than expected response in blood glucose levels." (PMID 33773581, 2021). "This analysis revealed that Hsp10 KD causes hypothalamic insulin resistance evidenced by a 35% reduction in insulin-induced T308 phosphorylation of AKT." (PMID 33946318, 2021). "We found more consistent evidence for an association of the insulin resistance phenotype of fasting insulin, triglycerides, and HDL with schizophrenia when we examined only genetic variants also associated with inflammation." (PMID 33711016, 2021). "The molecular mechanisms involved in T2DM are incompletely explained, but insulin resistance and defects in insulin secretion are the main causes of this disease." (PMID 34827690, 2021). "In insulin resistant fatty rat models, rosiglitazone treatment prevents the development of hypertension and partially restores the vasodilatory effects of insulin, thus ameliorating endothelial dysfunction associated with insulin resistance." (PMID 34966295, 2021). "Brain insulin resistance is the failure of brain cells to respond to insulin, this leading to insulin deficiency and impaired glucose transport inside the neurons." (PMID 34069618, 2021). "High prolactin exposure promotes β-cell replication, insulin secretion, and hyperinsulinemia, while it is also associated with impaired glucose tolerance and insulin resistance." (PMID 34684381, 2021). "Insulin resistance and insulin signaling pathways were also found to be associating with this module." (PMID 34707685, 2021). "Defects in the insulin signaling cascade has been associated with severe forms of insulin resistance and type 2 diabetes." (PMID 34946711, 2021). "The association of gut dysbiosis with insulin resistance is further verified by the observation that when the intestinal microbiota from lean donors was transferred to individuals with metabolic syndrome, insulin sensitivity was recovered." (PMID 34502047, 2021).
Insulin resistance (continued). "In summary, 7 days of HFD feeding caused WAT insulin resistance, reflected by reductions in insulin-mediated WAT glucose uptake and suppression of WAT lipolysis." (PMID 33411692, 2021). "β-cell dysfunction linked with decreases in insulin releases is likely to result in decreased insulin action in the brain, as well as weight gain and exacerbation of insulin resistance." (PMID 34944525, 2021). "The increased insulin production caused by insulin resistance in T2DM leads to chronic ER stress contributing to the death of β-cells by apoptosis." (PMID 34925466, 2021). "Liver function is known to be related to insulin resistance and metabolic syndromes associated with elevated insulin, triglyceride, and glucose index." (PMID 35056312, 2021). "Insulin resistance is a hallmark of type 2 diabetes, causing irresponsive insulin signaling in peripheral tissues." (PMID 33800074, 2021). "Overall, resistin levels were positively associated with age, hypertension, waist circumference, insulin levels and the degree of insulin resistance (HOMAIR), triglycerides and creatinine levels, and inversely with HDL-C concentrations." (PMID 34496965, 2021). "LTB4 was also shown to aggravate insulin resistance via promoting inflammation-associated insulin resistance by recruiting macrophages, and reduce insulin sensitivity directly in muscle and liver by binding to BLT1." (PMID 34803675, 2021). "Insulin resistance results in decreased insulin sensitivity, causing blood glucose to hardly back to a normal level and persistent hyperglycemia." (PMID 34163437, 2021). "It is a lifelong condition caused by insulin resistance, which is insulin inadequacy to evoke the anabolic response to glucose, specifically in skeletal muscle, liver, and white adipocytes." (PMID 33802091, 2021). "The hyperglycemia associated with DN is due to insufficient insulin secretion or insulin resistance, which produces hypoxia and causes excessive production of inflammatory cytokines." (PMID 33692782, 2021). "As insulin inhibits lipolysis in the adipocytes, insulin resistance in the adipose tissue causes increased release of FFAs." (PMID 33923817, 2021). "We analyzed the risk factors for insulin therapy, including clinical parameters, blood glucose levels, and insulin resistance and secretion capacity." (PMID 33776619, 2021). "This disease is associated with hyperglycemia and is characterized by insulin resistance and dysfunction or death of β-cells, leading to insufficient insulin secretion for glycemic homeostasis." (PMID 34484126, 2021). "It was found that HFD CM caused insulin resistance in L6-GLUT4myc myotubes compared with chow CM, as indicated by a blunted insulin-stimulated increase in glucose uptake." (PMID 34707570, 2021). "Insulin resistance and reduced secretion of insulin by pancreatic β cells are considered important pathogenic mechanisms of GDM." (PMID 33879746, 2021). "A Korean study revealed that Lp(a) levels were significantly negatively associated with fasting insulin levels, insulin resistance (IR), and insulin secretion (IS)." (PMID 34315495, 2021). "The model of the Mediterranean diet is based on low-glycemic index foods, which favor low levels of insulin and, more generally, a lower risk of developing insulin resistance." (PMID 34201382, 2021). "PD caused a decrease in fasting plasma (fP) glucose, fP insulin, and homeostasis model assessment of insulin resistance (HOMA-IR) and glycated hemoglobin (HbA1c) in the short run, contrary to CD." (PMID 33801152, 2021). "Accumulating evidence from human and animal studies has linked vitamin D status to insulin secretion and insulin resistance given that both vitamin D and its receptor complex play important roles in regulating the β-cell insulin secretion." (PMID 33567588, 2021). "Because of the lower insulin secretory capacity caused by hyperinsulinemia, it is less possible for obese people with HH to compensate for insulin resistance." (PMID 34441564, 2021).